GOLGA8K (golgin A8 family member K)
Tractability: No criterion of Open Targets' tractability assessment is met for any kind of drug.
Gene: Protein-coding gene on chromosome 15 (32,389,599 to 32,403,292, reverse strand). Ensembl gene ENSG00000249931.
Gene Ontology:
Biological process: Golgi organization
Cellular component: cis-Golgi network; Golgi cis cisterna; Golgi cisterna membrane; Golgi apparatus
Genetic constraint (gnomAD): Loss-of-function variants: 8 observed, 11.59 expected, observed/expected ratio (o/e) 0.69, 90% interval 0.4 to 1.24. The synonymous counts are far from expectation, so gnomAD's model fits this gene poorly and the ratio says little. Missense variants: 41 observed, 101.95 expected, observed/expected ratio (o/e) 0.4, 90% interval 0.31 to 0.52. Synonymous variants: 17 observed, 37.26 expected, observed/expected ratio (o/e) 0.46, 90% interval 0.31 to 0.68.
Homologues: Orthologues: mouse Golga2 (45% identical), dog GOLGA2 (44% identical), tropical clawed frog golga2 (34% identical), zebrafish golga2 (29% identical), Drosophila melanogaster GM130 (23% identical), Caenorhabditis elegans golg-2 (19% identical), rat Golga2l1 (5% identical). Paralogues in human: GOLGA8T (99% identical), GOLGA8H (97% identical), GOLGA8J (97% identical), GOLGA8M (96% identical), GOLGA8N (91% identical), GOLGA8O (90% identical), GOLGA8Q (90% identical), GOLGA8R (90% identical), GOLGA8S (84% identical), GOLGA8F (81% identical), GOLGA8G (81% identical), GOLGA8A (66% identical), and 6 more.